SHMT1 (serine hydroxymethyltransferase 1)
Diseases named in the same sentence as SHMT1 in open-access papers (continued):
Sharing a sentence is not in itself a finding about the gene and the disease.
tumor (40 papers, 2010 to 2026). "This impairment increases the risk of intestinal tumor formation in Apc^min/+ mice, indicating that Shmt1 contributes to CRC susceptibility through gene-diet interactions." (PMID 40738465, 2025). "Decreased SHMT1 level was associated with venous infiltration (P = 0.009), high tumor grade (P = 0.021) and advanced TNM stage (P = 0.019)." (PMID 30755243, 2019). "To determine if SHMT1 regulates phenotypes associated with tumor progression, we performed a wound-healing assay and Matrigel-based invasion assay." (PMID 28288142, 2017). "Overexpression of either IL-6 or IL-8 partially rescued SHMT1 loss-induced tumor growth inhibition and migration." (PMID 28288142, 2017). "Based on this evidence, we investigated whether Neu5Ac supplementation could rescue loss-of-SHMT1-mediated tumor cell growth inhibition and reduced migration phenotypes." (PMID 28288142, 2017). "To investigate this effect in vivo, we administered either 125 mM formate in drinking water or intraperitoneal AICAR injections (50 mg kg−1) to tumor‐bearing mice with Shmt1 KD or control tumors." (PMID 41195591, 2026). "Although our study has some limitations, the available data still support that SHMT1 inhibits tumor cell proliferation, invasion and EMT and increases the level of apoptosis by inhibiting AKT/FOXO3 A signaling pathway." (PMID 40442541, 2025). "Transcriptomic analysis of tumor samples from 97 NSCLC patients revealed significant upregulation of SHMT1 expression under low-folate conditions." (PMID 40738465, 2025). "Studies have shown that SHMT1 inhibits NADPH oxidase 1 in HCC, thereby reducing ROS levels, which in turn suppresses tumor cell invasion and metastasis, indicating that SHMT1 plays a critical role in maintaining metabolic homeostasis." (PMID 40738465, 2025). "SHMT1 acts as a tumor suppressor in HCC by suppressing NADPH oxidase 1, thereby reducing ROS levels and inhibiting epithelial-mesenchymal transition." (PMID 40738465, 2025). "Previous data indicated that FN-EDA promoted resistance of HCC cells to sorafenib by up-regulating the expression of SHMT1 in the tumor cells." (PMID 39286657, 2024). "The results showed that inhibiting NF-κB activation significantly suppressed the up-regulation of SHMT1 expression in tumor cells." (PMID 39286657, 2024). "In our study, we discovered that tumor cells exploit FN-EDA to induce the expression of SHMT1 via the TLR4/NF-κB pathway." (PMID 39286657, 2024). "Our analysis revealed that SHMT1 showed high expression in tumor cells that underwent local therapy." (PMID 39286657, 2024). "NOTCH1-mutated tumours did show higher expression of serine/glycine metabolism enzymes PHGDH, SHMT1 and SHMT2." (PMID 36932191, 2023). "In parallel, LF tumours expressed 2-fold higher SHMT1 and SHMT2 levels than did the paired adjacent lung tissue." (PMID 36615660, 2022). "Inhibiting SHMT1 offers potential therapeutic options for tumor patients with low SLC19A1 expression." (PMID 35531073, 2022). "3-bromopyruvate (3BP) can bind to the active site of SHMT1 (Cys204) to form the enzyme-3BP complex, which completely inhibits human SHMT1 to achieve an anti-tumor effect." (PMID 35531073, 2022). "Functional assays further confirmed that SHMT1 exerted tumor suppressive roles in HCC by inhibiting cell metastasis, EMT and MMP2 expression." (PMID 30755243, 2019). "Mechanistically, SHMT1 acted as a tumor suppressor by targeting NOX1 and subsequently restrained ROS production, EMT and MMP2 expression in HCC cells." (PMID 30755243, 2019). "High levels of PHGDH, PSPH, SHMT1 in tumor and PSPH in tumor stroma were correlated with high histological grading (p<0.001), ER negativity (p<0.001), PR negativity (p<0.001), and high Ki-67 LI (p<0.001)." (PMID 24979213, 2014). "In patients with Dukes' stage C or D HCY can be considered as a tumor marker only in case of SHMT1 1420CC genotypes." (PMID 20920350, 2010).
tumor (continued). "Notably, in NSCLC with concurrent LKB1 and KEAP1 mutations, SHMT1 expression is further upregulated through NRF2-mediated activation, contributing to serine-glycine 1-carbon metabolism and supporting tumor cell survival under oxidative stress." (PMID 40738465, 2025). "A recent multiomics study integrating single-cell and bulk RNA sequencing with metabolomics revealed that SHMT1 expression declined with decreasing tumor differentiation, with significantly lower levels in anaplastic thyroid carcinoma (ATC) compared with PTC or normal tissue." (PMID 40738465, 2025). "Next, we investigated whether sorafenib treatment led to an increase in the expression of SHMT1 in tumor cells." (PMID 39286657, 2024). "We believe that blocking FN-EDA-mediated SHMT1 activation represents a promising therapeutic strategy that could enhance the anti-tumor efficacy of sorafenib in the treatment of advanced HCC." (PMID 39286657, 2024). "Several studies have found that SHMT1 can promote tumor growth and progression." (PMID 36467068, 2022). "Inhibiting SHMT1 expression may be an emerging strategy for tumor patients with low SLC19A1 expression." (PMID 35531073, 2022). "However, the potential function of SHMT1 inhibitors has always been concerning for treating tumor diseases." (PMID 35531073, 2022). "Furthermore, silencing SHMT1 with low SLC19A1 expression inhibits tumor growth by impairing pyrimidine biosynthesis in vitro and in vivo, whereas silencing SHMT1 with SLC19A1 overexpression cannot alleviate tumor growth." (PMID 35531073, 2022). "SHMT1 acts as a tumor suppressor in HCC by inhibiting cell metastasis, EMT and MMP2 production." (PMID 30755243, 2019). "The expression of PSPH, tumor SHMT1 and matrix SHMT1 was higher in PTC than FTC." (PMID 31423225, 2019). "Expression of PHGDH, PSAT1, PSPH and tumor SHMT1 is higher in PDTC and PTC, but lower in MTC." (PMID 31423225, 2019). "Taken together, these data indicate that SHMT1 plays tumor suppressive role and may function as prognostic marker in HCC." (PMID 30755243, 2019). "Finally, to determine the role of IL-6 and IL-8 in mediating the tumor-promoting effect of SHMT1, we performed rescue experiments." (PMID 28288142, 2017). "Surprisingly, we did not observe any major negative impact of Shmt1 loss on tumor initiation and development in these models." (PMID 22438825, 2012). "Coexpression network analysis revealed that SHMT1 was significantly coexpressed with other OCM genes such as MTHFD1 and PSAT1, suggesting its potential role in maintaining metabolic homeostasis in tumor cells." (PMID 40738465, 2025). "Serine hydroxymethyl transferases (SHMTs), including SHMT1, the cytoplasmic isozyme, and SHMT2, the mitochondrial isozyme, are key enzymes in the 1C metabolism of tumor cells." (PMID 39286657, 2024). "Rabinowitz and his colleagues reported pyrazolopyran inhibitors of SHMT1 and −2 (SHIN1, SHIN2) that inhibited the proliferation of human tumor cell lines at sub-micromolar concentrations." (PMID 35008360, 2021). "In this study, both the data from public databases and the results obtained from our clinical specimens consistently showed reduced expression of SHMT1 in HCC, indicating a tumor suppressive role in HCC." (PMID 30755243, 2019). "To further validate the data from online datasets, we measured SHMT1 mRNA levels in 120 pairs of HCC tissues and adjacent non-tumor liver specimens." (PMID 30755243, 2019). "On the other hand, SLC6A6 and SLC22A4 are transporters, SART3 is a tumor rejection antigen, VPS41 is involved in organelle development, SEMA4C is involved in axon guidance, and SHMT1 is an enzyme with involvement in glycine, serine, and threonine metabolism." (PMID 30973896, 2019). "SHMT1 inhibited migration, invasion and EMT progression of HCC cells, and suppressed tumor metastasis of HCC in vivo." (PMID 30755243, 2019).
tumor (continued). "Aminopeptidase AAP-1 and serine hydroxymethyltransferase SHMT1 both showed PKM2- concentration dependence, and were upregulated in the tumor." (PMID 23154538, 2012). "SHMT (cytoplasmic, SHMT1; mitochondrial, SHMT2) catalyzes the transfer of a carbon unit from serine to tetrahydrofolate (THF), resulting in the formation of 5,10-methenyl-THF, which is crucial for nucleotide synthesis to promote rapid tumor proliferation." (PMID 40137165, 2025). "To date, however, no clear evidence has demonstrated a functional tumor-promoting or tumor-suppressive role for SHMT1 in PC, highlighting the need for further investigation." (PMID 40738465, 2025). "For both SHIN1/2 and AGF347, inhibition of both SHMT1 and SHMT2 was essential to their anti-tumor effects, as this prevents metabolic compensation for the loss of SHMT2 activity by reversal of the SHMT1 reaction and the synthesis of glycine and 5,10-methylene THF." (PMID 35008360, 2021). "BRAFV600E mutant cells have higher PHGDH, PSAT1, PSPH, tumor SHMT1, and interstitial SHMT1 and GLDC expression than non-mutant cells." (PMID 31423225, 2019). "AAP-S and SHMT1 correlated with the PKM2 expression level and were upregulated in the tumor." (PMID 23154538, 2012). "Nevertheless, our data suggest that tumor cells eventually will develop resistance to putative treatments directed against metabolic enzymes since tumor growth undoubtedly can occur in the absence of Shmt1, Phgdh or Ldha." (PMID 22438825, 2012).
infection (5 papers, 2013 to 2025). The state of being infected such as from the introduction of a foreign agent such as serum, vaccine, antigenic substance or organism. "Next, we used lentiviral infection to transfect sh-SHMT1 into T24 cells to further explore the effect of SHMT1 on the malignant progression of BC." (PMID 40442541, 2025). "In addition, genes related to glycerolipid metabolism (Plpp2), glycolysis metabolism (Pfkp), adipocyte differentiation (Rapgef4), nucleotide metabolism (Entpd3), serine catabolism (Shmt1), retinol metabolism (Akr1b10), and lipid-grading metabolism (Pla2g4f) were upregulated after EgPSC infection." (PMID 36713407, 2022).
cardiovascular disease (2 papers, 2017 to 2025). "More studies are needed to investigate the role SHMT1 rs11868708 plays in atherogenesis and subsequent cardiovascular diseases." (PMID 27822905, 2017). "This metabolic shift may contribute to an imbalance in energy metabolism in cardiomyocytes and to pathological cardiac remodeling, suggesting that SHMT1 is a key metabolic regulator in cardiovascular disease." (PMID 40738465, 2025).
mitochondrial disease (1 paper, 2016). "No proven mechanism yet connects mitochondrial disease to CFD, but given that brain expresses very little SHMT1, our results pose the hypothesis that CFD may result from impaired mitochondrial formate synthesis." (PMID 27307216, 2016).
neurological disorders (1 paper, 2025). "Beyond the developmental implications, SHMT1 polymorphisms have been associated with an increased risk of various neurological disorders, including NTDs and acute lymphoblastic leukemia." (PMID 40738465, 2025).
SHMT1 also shares sentences with these, for which no sentence is quoted: colorectal cancer (3 papers); Parkinson disease (3); adenocarcinoma (2); colorectal adenoma (2); glioblastoma (2); viral infection (2); acute kidney injury (1); Alzheimer disease (1); anaplastic carcinomas (1); asthma (1); autism (1); bone metastasis (1); childhood acute lymphoblastic leukemia (1); childhood asthma (1); clear cell renal cell carcinoma (1); dementia with Lewy bodies (1); gastric cardia adenocarcinoma (1); head and neck squamous cell carcinoma (1); hyperhomocysteinemia (1); Hypertension (1); liver disease (1); liver fibrosis (1); lymph-node metastasis (1); metabolic disease (1); metabolic dysfunction-associated steatotic liver disease (1); metastatic disease (1); multiple system atrophy (1); neurodegenerative disease (1); optic disc edema (1); papillary thyroid carcinomas (1).
A further 8 diseases each share a sentence with SHMT1 in 1 paper.